IL1B (interleukin 1 beta)
Diseases named in the same sentence as IL1B in open-access papers (continued):
Sharing a sentence is not in itself a finding about the gene and the disease.
cancer (continued). "Additionally, cancer cells at the advanced stage spontaneously secrete IL-1β where it can intrinsically activate pro-IL-1β and catalytic function of caspase-1." (PMID 27429614, 2016). "Previous studies showed that TNF-α and IL-1β are essential for bacterial cancer therapy." (PMID 27835896, 2016). "The proliferation of HCT116 cells caused by conditional medium was significantly blocked by IL-1RA treatment, and the reduction caused by IL-1RA was further reduced by GEN-27, which suggested a vital role of IL-1β in GEN-27-mediated inhibitory action on cancer cell proliferation." (PMID 27057094, 2016). "Measurement of IL‐1β, IL‐6, and TNFα serum levels may help identify early cancer progression among patients with CRP <5 mg/L in routine practice." (PMID 26799163, 2016). "The influence of IL-10 on more severe cancer disease is explained by antagonistic effect of IL-10 on the formation of pro-inflammatory cytokines (IL-6, TNF, IL-1α, IL-1β, IL-12) and inhibition of the inflammatory response, which plays an important role in the development of cancer." (PMID 27547238, 2016). "Important cytokines and mediators involved in the induction and perpetuation of the inflammatory environment in cancer, such as IL-6, IL-1β, macrophage colony-stimulating factor (M-CSF) and cyclooxygenase 2 (Cox2), have the transcription factor STAT3 as a crucial regulator of their expression." (PMID 26501341, 2015). "Percent of IL-1B-511*T carriers in cancer group has reached almost 69% of tested individuals." (PMID 26401131, 2015). "Taken together these data suggest that IL-1β and IL-1R1 promote cancer growth and metastasis by up-regulating CXCR4 expression and that CXCR4 may be a link between inflammation and cancer." (PMID 26176534, 2015). "Second, the cancer-bearing mice were treated with an interleukin-1 beta (IL-1β) neutralizing antibody to see whether IL-1β is involved in the cancer migration." (PMID 25706411, 2015). "In rats, an increase of IL-1β at mRNA or protein level was observed after spinal nerve injury, after hind paw and thoracic incisions, spinal cord injury, zymosan or formalin injection and in a cancer pain model." (PMID 26218747, 2015). "Pharmacological inhibition of Notch signaling reversed the up-regulation of CXCR4 induced by IL-1β, suggesting that Notch signaling may be involved in the growth and metastasis of cancers via up-regulation of CXCR4." (PMID 26176534, 2015). "However, the detailed mechanisms explaining the effect of IL-1β on cancer development are not fully understood." (PMID 26176534, 2015). "An inflammatory IL1B cytokine is involved in cancer onset and progression." (PMID 24618420, 2014). "Hence, the treatment of cancers with IL-1 blockade, particularly by blocking IL-1β activity, appears to be a promising strategy, especially in addition to antiangiogenic therapies." (PMID 24901233, 2014). "PTEN can be inhibited in cancer cells upon induction of the pro-inflammatory cytokine IL-1β." (PMID 24571667, 2014). "Additionally, long term use of non-steroidal anti-inflammatory drugs (NSAIDs) which inhibit pro-inflammatory cytokines, like TNF-α and IL-1β, decrease cancer incidence." (PMID 25056661, 2014). "At high levels of IL-1β, cancer cells that receive genotoxic insults engage the apoptotic pathways." (PMID 24348858, 2014). "Composition of intestinal microbiota, however, may also affect cancers distal to the GI track due to the global effect of inflammasome activation and IL-1β or IL-18 secretion." (PMID 24474192, 2014). "The inability of urinary IL-1β to differentiate between benign and malignancy may be confounded by the inflammatory nature of so many benign and cancer conditions." (PMID 25403235, 2014).
cancer (continued). "Overexpression of IL-1β was found to induce gastric inflammation and cancer in mice." (PMID 24223129, 2013). "In conclusion, this study demonstrated the up-regulation of IL-1β in EGF-treated cancer cells." (PMID 23383347, 2013). "Several molecular mechanisms of cancer development in IL-1β transgenic mice have been suggested." (PMID 24216700, 2013). "The activation of EGF signaling and increase of IL-1β contributed to chemotherapeutic resistance of cancer cells, suggesting that the expression of IL-1β may be used as a biomarker to evaluate successful cancer treatment." (PMID 23383347, 2013). "For postmenopausal women, IL1B-rs1143627 (OR=1.80, P=0.02) and IL1B-rs16944 (OR=1.85, P =0.02) were associated with risk among EA women, with significant associations for TNFA-rs1799724 limited to estrogen receptor (ER) positive cancers (OR=2.0, P =0.001)." (PMID 23991131, 2013). "In the stratification analysis of source of control, significantly increased risk between the IL-1B +3954C/T polymorphism and cancer risk was detected among hospital-based studies, but not among population-based studies." (PMID 23704929, 2013). "Finally, Il-1β is a primary mediator of innate and adaptive immune responses and has been firmly established as a regulator of cancer progression via control of proliferation and apoptotic processes." (PMID 23029096, 2012). "Nonetheless, this result suggests that Zeb1 may be involved in IL-1β-mediated reactivation or de novo induction of cancer stem cells." (PMID 23174018, 2012). "Similarly, production of pro-inflammatory cytokines (IL-6, IL-8, IL-12p70, TNF-α and IL-1β) was strongly inhibited by TLR7 ligand in two cancer-derived HPV cell lines." (PMID 22513098, 2012). "We thus initiated our research to investigate whether inducible HSP70 was synthesized upon IL-1β stimulation in HeLa cells, which are human epithelial carcinoma cells, and we found an obvious increase of HSP70 level." (PMID 23185533, 2012). "To investigate the effects of increased gene expression of ephrin B1 in the mouse model of cancer-induced pain, we examined the change in the inflammatory mediator IL-1β in the cancer-inoculated region of the right hind paw by double sandwich enzyme-linked immunosorbent assay (ELISA)." (PMID 20979661, 2010). "Notably, Z-360 relieves cancer-induced pain by preventing this pain cascade through the suppression of IL-1β production, likely via the blockade of CCK1 receptor." (PMID 20979661, 2010). "Since previous studies have indicated that changes in miR-146a expression might regulate proliferation in a range of cancer cell lines we therefore decided to investigate whether IL-1β-induced miR-146a expression might regulate HASM proliferation." (PMID 20525168, 2010). "Cocktail 1 was designed as in a previous reported cocktail, where the combination of poly I:C, IFNα, IFNγ, TNFγ and IL-1β showed very potent IL-12p70 stimulating properties compared to the standard DC cocktail used for DC based cancer vaccines, containing IL-6, TNFα, IL-1β and PGE2." (PMID 20663192, 2010). "Obviously, the magnitude of immune cell infiltration might also have an indispensable role in the complex interactions between IL-6 and sIL-6R in cancer stroma, because IL-6, IL-1β, and in part sIL-6R are produced by cancer cells, as well as by immune cells." (PMID 20823887, 2010). "Based on the results of these studies, we therefore hypothesised that ephrin B-Eph B receptor signalling and IL-1β play a role in cancer-induced pain." (PMID 20979661, 2010). "These known NF-κB target genes, such as IL6, IL8, BIRC2 (clAP-1), ICAM1, YAP1, CDKN1A (p21), CSF2, CCDN1, IL1A, IL1B, and so on, include many that have been independently confirmed to be differentially expressed and pathologically implicated in HNSCC and other cancers." (PMID 18334025, 2008). "IL-1β has been found to induce NF-κB activation in cancer cells such as leukaemic cell line OCIM2." (PMID 16721367, 2006).
cancer (continued). "Finally, results of the population study from the European Prospective Investigation into Cancer and Nutrition Potsdam indicated a significant interaction between plasma IL-1β, IL-6 and type II diabetes development." (PMID 15904534, 2005). "In order to demonstrate whether NSCLC-derived TEVs were able to mediate cancer progression by modulating the immune response, the levels of the immune checkpoint PD-L1 in TEVs isolated from unstimulated and IL-1β-stimulated cells as well as in OR cells were assessed." (PMID 40725070, 2025). "Importantly, this same inflammatory potential also links IL-1β to cancer progression." (PMID 41440367, 2025). "Additionally, cancer cachexia is associated with decreases in serum albumin, triglycerides (TG), cholesterol, high-density lipoprotein (HDL), and low-density lipoprotein (LDL) and increases in pro-inflammatory cytokines such as IL-6, IL-1β, and TNF-α." (PMID 40469669, 2025). "In addition, IL1B involves in the development of various cancers." (PMID 39816677, 2025). "Increased expression and secretion of IL-1β by cancer stem cells might activate the autocrine signaling loop by stimulating signaling pathways (such as NF-κB and cAMP-response element binding protein pathways) and promoted epithelial mesenchymal transformation, cell invasion and metastasis." (PMID 40839565, 2025). "It has been shown that these upregulated hub genes are associated with many cancer risks and may serve as potential biomarkers or therapeutic targets for BC, especially FNI and IL1B, which were upregulated in the expression of both low-grade and high-grade BC cell-derived EVs." (PMID 39816677, 2025). "In this context, it is also reasonable to ask whether cancer cells are endowed with constitutively active inflammasome activity and/or utilize alternate mechanisms for IL-1β transcription, cleavage of its pro-form, and secretion of the fully active form in the extracellular space." (PMID 39858071, 2025). "Additionally, it has been observed that OC cells are able to secrete lactate to promote the synthesis and secretion of IL-1β by TAMs, and the secreted IL-1β activates the nuclear factor kappa-B (NF-κB) signaling pathway in cancer cells to induce the up-regulation of the expression of PD-L1 and CCL2." (PMID 40045411, 2025). "Furthermore, the 16-week therapeutic yoga program (TYP) randomized trial (NCT01654289) modifies the cytokine profile of IL-1β and IL-1Ra, which are considerably down-regulated in older women with heterogeneous cancer survival as well as decrease in overweight or obese cancer survivors." (PMID 40584290, 2025). "Moreover, the expression levels of IL-6 and IL-1β were significantly elevated in the cancer group." (PMID 41267807, 2025). "IL-1β, as the transcriptional product of IL1B, can regulate gene expression and cytokine production, modulate cell adhesion and migration, and participate in angiogenesis or immune responses, exerting pleiotropic effects in cancer development, migration, and metastasis." (PMID 39883700, 2025). "Within the TME, adipocytes, known as cancer-associated adipocytes (CAAs), play a pivotal role in promoting BC development through various signaling pathways, including the fibroblast growth factor (FGF), the vascular endothelial growth factor (VEGF), and Interleukin-1 beta ( IL-1β)." (PMID 38780753, 2024). "The decrease in their proliferation potential may be attributed to the secretion of several inflammatory molecules, such as IL-1β, IL-6, IL-8, IL-10, and matrix metallo-proteinases (MMPs) by cancer cells, which have adverse effects on the neighboring cells in the niche." (PMID 39768220, 2024). "Interestingly, drugs targeting pro-inflammatory molecules such as anti-TNF-α and anti-IL-1β are emerging as highly promising options for pain control and could potentially be employed in managing cancer pain." (PMID 38433844, 2024). "However, the precise role of IL-1β in cancer initiation remains insufficiently explored." (PMID 38671854, 2024).
cancer (continued). "Moreover, in the BM of MM patients, cancer cells stimulate the secretion of IL-1β and IL-6." (PMID 38610941, 2024). "Although our analysis requires a large-scale validation, it suggests a potential mechanism-based selection strategy, in which patients with a higher expression of IL-1β in BC tissue may have a better immune response and probably a better response to cancer treatments." (PMID 38397123, 2024). "IL-1β may play an important role in aiding cancer metastasis, angiogenesis, and growth." (PMID 39451257, 2024). "However, it has recently been shown that IL‐1β may be involved in malignant tumor progression by other mechanisms." (PMID 38798075, 2024). "The fact that so many cancer cells displayed immunoreactivity for both proteins implies that a positive feedback mechanism may exist in which IL-1β is secreted by the cancer cell and binds to the receptor on the same cell, activating NF-ĸB, which, in turn, activates iNOS expression." (PMID 38187473, 2023). "However, IL-1β and IL-18 are able to promote T cell immunity against cancer in other cases." (PMID 36932407, 2023). "However, IL-1β blockade has also provided benefits in treating cancer." (PMID 37461742, 2023). "IL-1β may also have a positive feedback loop, perpetuating the course of the cancer." (PMID 37511306, 2023). "In addition, IL1β and TNFα released by cancer cells increase TGF-β2 expression in astrocytes." (PMID 36835266, 2023). "Moreover, fibroblasts cultured with exosomes derived from OS cells exhibited elevated expression of pro-inflammatory genes, including IL-1β, IL-6, and IL-8, which significantly influence the regulation of the inflammatory microenvironment and the advancement of cancer." (PMID 37990331, 2023). "Inflammasomes and their effectors such as IL-1β and IL-18 significantly contribute to establishment of inflammation, while the TME is enriched in damage-associated molecular patterns (DAMPs) that have been shown to drive inflammasome activation in both immune and cancer cells." (PMID 36032139, 2022). "Particularly, tumour necrosis factor-α (TNF-α), interleukin-1β (IL-1β), and hepatocyte growth factor (HGF) have all been shown to cause mesothelial cell retraction, exposure of the underlying ECM, while facilitating the adhesion of cancer cells to the mesothelial cell monolayer." (PMID 36494669, 2022). "Cancer may take advantage of IL-1β degradation to evade immunity." (PMID 36132127, 2022). "In summary, macrophages could induce the activation of DLL3-dependent Notch1/Notch2 signaling, the upregulation of IL-33, and the degradation LG3BP and HSPA8, resulting in enhanced cancer-cell proliferation and elevated IL-1β, IL-12, and IL-10 secretion by macrophages." (PMID 35382168, 2022). "Although the abundance of cytokines, such as CCL18 and IL1b, in cancer cells may be responsible for initiating NF-kB signaling through activation of IKK in the CAF subset, numerous feedback loops in the TME lead to the failure of therapeutic strategies to target inflammatory factors." (PMID 35189958, 2022). "Similarly, decursinol angelate (DA), an AGN-derived compound, inhibited pro-inflammatory cytokines associated with cancer cell proliferation, including TNF-α while decursin blocked lipopolysaccaride-induced expression of MCP-1, IL-8, TNF-α, and IL-1β in cells and attenuated IL-1β and TNF-α." (PMID 36249788, 2022). "Moreover, the findings support that IL-1β blockade might be suitable for therapy for KRAS-mutant cancers." (PMID 35327394, 2022). "Notably, IL-1β can not only act as a pleiotropic cytokine to promote cancer progression in the tumor microenvironment but can also gain access to the brain through passive diffusion, subsequently interacting with IL-1R1 expressed on endothelial cells at the blood–brain barrier or vagal afferents." (PMID 35246220, 2022). "However, IL-1β was shown to be involved in cancer more than IL-1α." (PMID 36132127, 2022).
cancer (continued). "IL-1β may be required for cancer recurrence by maintaining PD-L1 expression during chemotherapy." (PMID 35326493, 2022). "It includes seven ligands with pro-inflammatory activity (IL-1α, IL-1β, IL-18, IL-33, IL-36α, IL-36β, IL-36γ), as well as anti-inflammatory cytokines (IL-37 and IL-38), having crucial roles in host-defense responses, but also in inflammatory responses that contribute to cancer development." (PMID 33840390, 2021). "Thus, it is not surprising to see that treatment of cancer cells with IL1β caused a concerted increase in EMT as well as in PD-L1 levels; the consistency in these trends was also visible upon withdrawal of the signal." (PMID 34975907, 2021). "Cancer-associated fibroblasts (CAFs) are a dominant stromal cell type in the TME that are activated from resting fibroblasts via the NF-κB and JAK-STAT pathways once cancer cells or immune cells release signaling molecules such as TGFβ, RTK ligands, IL1β and IL6." (PMID 34202411, 2021). "Interestingly, the responsiveness of IL-1β was significantly correlated with overall survival, suggesting that this might be a useful prognostic biomarker for advanced cancer patients receiving fucoidan." (PMID 34436263, 2021). "Thus, the anti-inflammatory effect of flavonoids inhibits angiogenesis of cancer cells by decreasing inflammatory cytokines such as tumor necrosis factor-alpha, interleukin (IL)-1β, and IL-6, and the anti-estrogen effect prevents metastasis of cancer cells by decreasing aromatase activity." (PMID 34578927, 2021). "Furthermore, IL-1β induces IL-6 production by transglutaminase 2- (TG2-) expressing MCF-7 cells through NF-κB-, PI3K-, and JNK-dependent mechanisms, ultimately increasing the stem-cell-like phenotype of cancer cells associated with drug resistance." (PMID 34602858, 2021). "However, there were IL-4, IL-17, and IL-1β decreases in the patients with cancer (p < 0.05)." (PMID 34518597, 2021). "Thus, in an indirect process, IL1β gives rise to the differential sensitivity of CRC cancer cells." (PMID 34066976, 2021). "IL‐1β is of great importance in inflammation and could stimulate cancer malignant potential." (PMID 33955688, 2021). "Besides this, IL-1β has been described a promotor of angiogenesis and cancer cell metastasis." (PMID 33584721, 2020). "Damage associated molecular patterns (DAMPs) from necrotic and dying cancer cells are sensed by CAFs causing activation of the NLRP3 inflammasome pathway (protein complexes that mediate inflammatory response to pathogen, stress, and tissue injury leading to cytokine release) and secretion of IL-1β." (PMID 32957515, 2020). "However, whereas glucose carbons are required for generation of novel biomass supporting proliferation of cancer cells, Warburg-like enhancement of glucose metabolism drives production of inflammatory cytokines, such as IL-1β, in classically activated macrophages." (PMID 33311467, 2020). "Furthermore, the addition of IL6 or IL1β neutralizing antibodies to the co-culture system between luc-AsPC-1 cells and human SCs significantly impaired cancer cell dissemination in vivo, as shown by a lower incidence of lung metastasis and a decreased bioluminescence signal." (PMID 32308766, 2020). "However, both TNF-α and IL-1β also upregulate Oct4 expression in cancer cells, which may counterbalance the antitumor activity of M1 macrophages." (PMID 32487125, 2020). "Reports from the literature suggest the significant inhibition of IL-1β in response to pyrazinib (P3) is a positive effect which may contribute to the anti-cancer activity of this drug in addition to its effects on oxidative phosphorylation in vitro and ex vivo and radiosensitivity in vitro." (PMID 32694701, 2020). "Cytokines and other compounds such as DCA, IL-1β, tumor necrosis factor α (TNF-α) and lipopolysaccharide (LPS) may promote expression of COX-2 mRNA and protein in human colorectal fibroblasts, profoundly in cancer-associated fibroblasts (CAF) 25-27." (PMID 32410839, 2020).